CD4 (CD4 molecule)
Diseases named in the same sentence as CD4 in open-access papers (continued):
Sharing a sentence is not in itself a finding about the gene and the disease.
HIV-1 infection (continued). "For this, mo-DCs from 6 ART naive patients in advanced stage of HIV-1 infection (mean CD4+ T-cell counts: 225 ± 37) were treated with either siRNA to silence the expression of SOCS-1 gene or scrambled non-silencing RNA following LPS-stimulation for 48 hours." (PMID 26492336, 2015). "These drugs cause immunosuppression, modulate the expression of chemokine receptors on CD4+ T lymphocytes, and influence the outcome of HIV-1 infection." (PMID 26539167, 2015). "Quiescent CD4+ T cells restrict human immunodeficiency virus type 1 (HIV-1) infection at early steps of virus replication." (PMID 26020637, 2015). "A putative association between HLA-A*74:01 and a favorable CD4:CD8 ratio is rather consistent with previous reports based on analyses of HIV-1 acquisition, VL and/or CD4 count after HIV-1 infection." (PMID 26191056, 2015). "RIPK1 and RIPK2 were cleaved during HIV-1 infection of T cell lines or primary activated CD4+ T cells." (PMID 26297639, 2015). "The adenovirus-mediated expression of Nef in macrophages induces chemokine production that results in chemotaxis and activation of CD4+ T cells for productive HIV-1 infection." (PMID 25835530, 2015). "Compared with control-LNA antagomirs, mir-29-LNA antagomirs significantly abrogated the ability of IL-21 to inhibit HIV-1 infection in CD4 T cells, indicating that the antiviral activity of IL-21 was at least in part mediated by miR-29." (PMID 26108174, 2015). "More recently, another receptor for cocaine, dopamine D4 receptor (D4R), was shown to mediate the drug-induced enhancement of HIV-1 infection in quiescent CD4+ cells, as evidenced by increased reverse transcription kinetics." (PMID 26539167, 2015). "In this study, we report a novel antiviral activity of IL-21 that is mediated by miR-29 and results in suppressed HIV-1 infection in primary lymphoid CD4 T cells." (PMID 26108174, 2015). "Recently, CRISPR/Cas9 system as a novel method of gene editing was used to disrupt CCR5 in T cell lines, primary CD4+ T cells, or induced pluripotent stem cells (iPSCs) to make them or their progeny cells resistant to HIV-1 infection." (PMID 26588898, 2015). "In contrast, sCD4–183, a small gp120-neutralizing reagent (26kD) was able to equally inhibit all three modes of infection, namely cell free, IFN-α-DC-mediated and LPS-DC-mediated HIV-1 infection of CD4+ T cells." (PMID 25760631, 2015). "We observed a significant increase in productive infection following HIV-1 infection in all APC co-cultured with T-cells compared to resting CD4+ T-cells cultured alone (p = 0.03 for all APC co-cultures)." (PMID 26362311, 2015). "Cellular activation, or addition of exogenous deoxyribonucleosides, relieves the post-entry block to HIV-1 infection in resting CD4+ T cells." (PMID 26020637, 2015). "The increased susceptibility of T cells from the elderly to HIV-1 infection correlated directly with CXCR4 and inversely with CD4 expression." (PMID 26452480, 2015). "Here we show that Vpr promoted HIV-1 infection of CD4+ T cells by counteracting an antiviral restriction in infected primary macrophages." (PMID 26186441, 2015). "Latent HIV-1 infection of resting memory CD4+ T cells is established when activated CD4+ T cells return to a quiescent state or through infection of quiescent T cells." (PMID 26485194, 2015). "During HIV-1 infection, Nef down-regulates the surface expression of the CD4 and selective MHC class I receptors, thereby avoiding lytic HIV-1 superinfections and early elimination of HIV-1-infected cells by natural killer cells and cytotoxic T cells." (PMID 29061947, 2015). "Because CD4 is the main receptor for HIV-1 infection, these results suggest that CD4 molecules displayed on the surface of exosomes can bind to envelope proteins of HIV-1 hindering virus interaction with target cells and infection." (PMID 25423108, 2014). "The latent reservoir in resting memory CD4+ T cells represents a major obstacle towards curing HIV-1 infection." (PMID 24489654, 2014).
HIV-1 infection (continued). "Because of the similarities between CVID and HIV-1 disease, it is not unexpected that IVIg treatment can have modest effects on T cell activation and CD4 count in HIV-1 infection." (PMID 25566250, 2014). "The Affinofile system, based on a CD4 and CCR5 dual-inducible cell line, permits quantitative characterization of HIV-1 infection across 24–48 distinct combinations of CD4/CCR5 expression levels." (PMID 24957778, 2014). "In a SIV animal model, IL-2 treatment resulted again in Treg expansion but also promoted CD4+ T cell activation and spontaneous apoptosis, further highlighting the difficulties of using IL-2 in vivo to modulate the course of HIV-1 infection." (PMID 24498287, 2014). "Combination antiretroviral therapy (cART) can effectively suppress HIV-1 replication, but the latent viral reservoir in resting memory CD4+ T cells is impervious to cART and represents a major barrier to curing HIV-1 infection." (PMID 24489654, 2014). "This has produced a novel set of evidence that supports a model whereby productive HIV-1 infection in macrophages requires CD4 localization to DRM and occurs via a DRM-dependent endocytic uptake pathway." (PMID 24465876, 2014). "One group progressed to CD4 counts below 200 cells/μl within 2 years of HIV-1 infection (CD4 Low Group), while the other group maintained CD4 counts above 500 cells/μl (CD4 High Group)." (PMID 25104967, 2014). "Subsequent, in vitro studies demonstrated that IFNγ treatment can enhance HIV-1 infection in both primary macrophages and CD4+ T cells, suggesting that these immune cell subsets were responsible for the original observation of HIV-1 infection of PBMC." (PMID 24454311, 2014). "In particular, a significant correlation was found between the ARSSS and the baseline CD4+ cell count, the baseline viral load, and the setpoint viral load in untreated patients with a primary HIV-1 infection." (PMID 25490090, 2014). "Meanwhile, we also found that HIV-1 infection induced necroptosis in CD4+ T-cell lines such as Jurkat, H9 and SupT1." (PMID 24714696, 2014). "To investigate a possible physiological role for this novel activity of Nef, we performed in vitro HIV-1 infection assays in the presence of exosomes from CD4− and CD4+ T cells, and also Nef expressing CD4+ T cells." (PMID 25423108, 2014). "Human pDC are rapidly activated by HIV-1 infection and the level of pDC activation is reversely correlated with CD4+ T-cell numbers, which is consistent with the observation from HIV-1 infected patients and SIV infected monkeys." (PMID 25077616, 2014). "Exposure to E.coli enhanced HIV-1 infection and CD4+ T depletion, and significantly increased the number of apoptotic p24+ cells." (PMID 24495380, 2014). "In fact, increased rates of proliferation of both CD4 and CD8 T cells are a hallmark of chronic HIV-1 infection." (PMID 25610441, 2014). "A significantly higher T-regulatory cell (Treg) frequency coupled with the high FoxP3 expression in the CD4 T-cells indicated an immunosuppressive environment in the advance stage of HIV-1 infection." (PMID 25198707, 2014). "Concordant with previous NHP studies we observed a massive depletion of CD4+ and CD4+CCR5+T cells in the colon within days of HIV-1 infection correlating with the colonic HIV RNA." (PMID 25503054, 2014). "CD4 is a receptor molecule required for HIV-1 infection and its removal from the surface of infected cells by Nef is thought to prevent multiple rounds of re-infection." (PMID 25423108, 2014). "To date, the mechanisms that lead to CD4 depletion from the surface of infected cells during HIV-1 infection are still only partially characterized." (PMID 25496667, 2014). "The data presented here support this model, as DRM mutants of CD4 led to decreased productive HIV-1 infection." (PMID 24465876, 2014). "Major efforts to investigate the mechanisms of HIV-1 mediated CD4+ T cell depletion have been made using ex vivo models of HIV-1 infection in primary human CD4+ T cells or cell lines." (PMID 24495380, 2014).
HIV-1 infection (continued). "This revealed efficient HIV-1 infection of the reporter T cells that was greater in magnitude from MDMs initially cocultured with infected CD4+ T cells than infected across transwells, and infection was abolished by AZT." (PMID 25467409, 2014). "HIV-1 infection is characterized by high levels of virus replication, gradual peripheral CD4+ T cell depletion, and aberrantly high immune activation." (PMID 24495380, 2014). "To date, very limited information exists as to which cell death pathway(s) are triggered in human LP CD4+ T cells by R5-tropic HIV-1 infection." (PMID 24495380, 2014). "The impact of HIV-1 infection on genes involved in ribosome biogenesis was further validated in primary CD4+ T cells." (PMID 25462981, 2014). "Overcoming the bias of using VSV-pseudotyped HIV-1 in our earlier studies, ectopic CD4 expression in primary astrocytes led to robust wild-type HIV-1 infection, demonstrating that the intracellular environment in astrocytes is conducive to viral replication." (PMID 25188302, 2014). "T cell exhaustion in HIV-1 infection is associated with increased expression of programmed death-1 (PD-1) and CD57 on the surface of CD4+ and CD8+ T cells." (PMID 24626392, 2014). "The effectiveness was demonstrated here for the first time by knocking down the HIV-1 receptor CD4 in macrophages and measuring the effect on HIV-1 infection." (PMID 24465876, 2014). "Human immunodeficiency virus type 1 (HIV-1) infection is characterized by progressive depletion of CD4+ T lymphocytes and dysfunction of the immune system." (PMID 24714696, 2014). "In contrast, exosomes released by CD4− T cells or CD4+ T cells expressing Nef are inefficient in preventing HIV-1 infection." (PMID 25423108, 2014). "Lower CD4+ T cell counts and a rapid decline of these cells were observed during the early phase of HIV-1 infection in South African women carrying this particular SNP." (PMID 25047784, 2014). "The data establish the Lamina Propria Aggregate Culture (LPAC) model as a robust and versatile platform for studying the impact of R5-tropic HIV-1 infection and commensal microbial species on mucosal CD4+ T cell death." (PMID 24495380, 2014). "METH also interferes with the normal antigen processing and phagocytic functions of macrophages, enhances the susceptibility of macrophages to HIV-1 infection by up-regulation of CCR5 and increases HIV-1 replication in CD4 T cells and monocytes." (PMID 24894206, 2014). "CD4+ T cell depletion following HIV-1 infection was reproducibly observed by 6 days post infection (dpi)." (PMID 24495380, 2014). "Resting CD4 T cells are important early targets of HIV-1 infection in which HIV-1 must overcome intrinsic barriers to viral replication." (PMID 25330112, 2014). "Consistent with a previous study in CD4+ T cell cultures in vitro, WT HIV-1 infection significantly enhanced the mRNA expression of APOBEC3D, APOBEC3F, and APOBEC3G." (PMID 25330146, 2014). "We conclude that exosomes released by CD4+ T cells inhibit HIV-1 infection and that Nef hinders this inhibitory effect by reducing the amount of CD4 on the surface of exosomes, thus promoting viral spreading." (PMID 25423108, 2014). "Chronic immune activation induced by HIV-1 infection is highly correlated with CD4 T cell depletion and immunodeficiency." (PMID 25077616, 2014). "Associations of full-length KIR2DS4 gene with longitudinal viral load (VL) and CD4+ T-cell (CD4) count in 207 youth with chronic (seroprevalent) HIV-1 infection." (PMID 24901871, 2014). "We have utilized this cytokine to provide a convenient in vitro model for HIV-1 infection and latency after direct infection of resting CD4+ T cells." (PMID 25330112, 2014). "Having shown that LCK expression in macrophages leads to elevated levels of CD4 at the surface, the impact this has on the different stages of HIV-1 infection was evaluated using a panel of assays as readouts for sequential stages of HIV-1 infection." (PMID 24465876, 2014).
HIV-1 infection (continued). "Since T CD4 count was low at entry (208/uL), he was treated (Truvada/Ritonavir/Reyataz) as soon as HIV-1 infection was discovered." (PMID 24964202, 2014). "HIV-1 infection increased the percentage of CD4+ T cells expressing both apoptotic and necrotic phenotypes relative to mock." (PMID 24495380, 2014). "The early activation marker CD69 on CD4+ T cells was also quantified because CD69+CD4+ T cells have been demonstrated as a major early target for HIV-1 infection." (PMID 24454812, 2014). "As in HIV-1 infected human patients, a decrease of total number of human leukocytes was induced by HIV-1 infection in humanized mice, as measured by cell numbers of human CD4, CD8 T cells and total CD45+ leukocytes in lymphoid organs." (PMID 25077616, 2014). "A major barrier to the elimination of HIV-1 infection is the presence of a pool of long-lived, latently infected CD4+ memory T-cells." (PMID 24651404, 2014). "HIV-1 infection results in persistent viral replication, CD4 depletion in peripheral blood and lymphoid organs." (PMID 25077616, 2014). "In our observations, hStau-2 expression was upregulated upon HIV-1 infection of CD4 + T lymphocyte cell line SUP-T1." (PMID 24520823, 2014). "In total, p24+ cells accounted for 39% of the CD4+ T cell death in the presence of E. coli, in sharp contrast to HIV-1 infection only." (PMID 24495380, 2014). "In particular, cells of the monocyte/macrophage lineage together with CD4+ T cells are the primary targets for HIV-1 infection in vivo, and HIV-1-infected monocytes have been identified in the peripheral blood of viremic and HAART-treated patients." (PMID 24736215, 2014). "HIV-1 RNA levels and CD4+ T-cells numbers are indicators of the clinical stage of infection and are considered prognostic factors for the evaluation of the course of HIV-1 infection." (PMID 24719500, 2014). "Upon HIV-1 exposure, human genital mucosal epithelial cells produce thymic stromal lymphopoietin (TSL), a secreted factor leading to maturation of DCs that also triggers DC-mediated amplification of HIV-1 infection in activated CD4+ T cells." (PMID 25033082, 2014). "Despite this variability, the Vpu functions of targeting CD4 and counteracting both physical virus restriction and NF-κB activation by tetherin are rigorously maintained throughout HIV-1 infection." (PMID 24465210, 2014). "Three HIV-1 proteins are known to play a role in CD4 down-modulation during HIV-1 infection: Env, Vpu and Nef." (PMID 25496667, 2014). "Our results showed that the presence of CD4+ exosomes also decreases the efficiency of HIV-1 infection in vitro." (PMID 25423108, 2014). "The CD4+ T cell depletion observed during HIV-1 infection is one of the primary mechanisms for HIV-1 pathogenesis." (PMID 24714696, 2014). "Together, the results indicate that CD4+ exosomes are detrimental to HIV-1 infection because of unproductive Env-mediated interaction with CD4 molecules exposed on the surface of exosomes." (PMID 25423108, 2014). "We developed a novel in vitro CD4+ T cell infection assay to quantify the level and distribution of HIV-1 infection in CD4+ T cell subsets including the newly described TSCM subset." (PMID 24517971, 2014). "We have previously reported that human pDC are rapidly activated by HIV-1 infection in humanized mice and the level of pDC activation is correlated with CD4+ T-cell depletion." (PMID 25077616, 2014). "Residues in domain 1 of human CD4 are required for the interaction with gp120 and HIV-1 infection, so domain 1 and 2 of the chimera were derived from the human gene." (PMID 24465876, 2014). "Strikingly, exosomes released by CD4+ T cells strongly inhibit HIV-1 infection in vitro in a concentration-dependent manner." (PMID 25423108, 2014). "Human hematopoietic cells derived from transplanted human stem cells have been shown to repopulate the GALT of BLT mice, and HIV-1 infection of these mice results in CD4 T cell depletion, initially in GALT and then systemically." (PMID 24497830, 2014).